SKIDA1 (SKI/DACH domain containing 1)
Synonyms: C10orf140; FLJ45187; DLN-1
Tractability: PROTAC: UniProt records ubiquitination sites on it.
Gene: Protein-coding gene on chromosome 10 (21,513,475 to 21,526,368, reverse strand). Ensembl gene ENSG00000180592.
Subcellular location (Human Protein Atlas): Nuclear bodies; Cytosol; Nucleoplasm
Gene Ontology:
Molecular function: DNA-binding transcription factor activity
Biological process: regulation of transcription by RNA polymerase II
Genetic constraint (gnomAD): Loss-of-function variants: 18 observed, 44.55 expected, observed/expected ratio (o/e) 0.4, 90% interval 0.28 to 0.6. The synonymous counts are far from expectation, so gnomAD's model fits this gene poorly and the ratio says little. Missense variants: 1,104 observed, 1,114.3 expected, observed/expected ratio (o/e) 0.99, 90% interval 0.94 to 1.04. Synonymous variants: 579 observed, 477.86 expected, observed/expected ratio (o/e) 1.21, 90% interval 1.13 to 1.3.
Homologues: Orthologues: macaque SKIDA1 (98% identical), rat Skida1 (94% identical), mouse Skida1 (93% identical), pig SKIDA1 (87% identical), dog SKIDA1 (87% identical), guinea pig SKIDA1 (81% identical), rabbit SKIDA1 (63% identical), tropical clawed frog skida1 (51% identical). Paralogues in human: EPOP (11% identical), SIMC1 (7% identical).
Diseases named in the same sentence as SKIDA1 in open-access papers:
SKIDA1 is named in the same sentence as 6 diseases in open-access papers, as found by Europe PMC text mining. Sharing a sentence is not in itself a finding about the gene and the disease. The quoted sentences say what the papers report.
acute leukemia (2 papers, 2022 to 2023). A clonal (malignant) hematopoietic disorder with an acute onset, affecting the bone marrow and the peripheral blood. "MLLT10 (also known as AF10) and SKIDA1 are commonly observed in acute leukemias and are indicative of a poor prognosis." (PMID 37236919, 2023). "Although all genes presented variable expression in individual subgroups of acute leukemia, SKIDA1 had pronounced expression in KMT2A-r compared to the remaining subgroups in all acute leukemia subtypes." (PMID 35734412, 2022). "SKIDA1 expression may predict those rearrangements in most subtypes of acute leukemia, while LAMP5 presents good performance to point out KMT2A-r in B-ALL and ALAL, including the KMT2A-USP2 fusion." (PMID 35734412, 2022). "The SKIDA1 (AUC: 0.839; CI: 0.799–0.879) and LAMP5 (AUC: 0.746; CI: 0.685–0.806) overexpression were the better markers associated with KMT2A-r compared to CSPG4 (also named NG2; AUC: 0.722; CI: 0.659–0.784), regardless of the type of acute leukemia." (PMID 35734412, 2022). "Therefore, we were able to point out biomarkers (e.g., SKIDA1 and LAMP5) to predict KMT2A-r regardless of acute leukemia subtypes." (PMID 35734412, 2022).
leukemia (2 papers, 2022 to 2025). A malignant (clonal) hematologic disorder, involving hematopoietic stem cells and characterized by the presence of primitive or atypical myeloid or lymphoid cells in the bone marrow and the blood. "Because KMT2A is a promiscuous gene and the distribution of fusion partners varies according to leukemia subtypes, we hypothesized that SKIDA1 and LAMP5 expression could be associated with specific gene rearrangements." (PMID 35734412, 2022). "SKIDA1 was also described as the best predictor of KMT2A (Mixed-lineage-leukemia) gene rearrangements." (PMID 40240354, 2025). "Considering each subtype of leukemia, the most divergent performance was observed in T-ALL, in which SKIDA1 had the best estimates (AUC: 0.991; CI: 0.981–1.000), followed by LAMP5 (AUC: 0.716; CI: 0.570–0.861), and CSPG4 (AUC: 0.558; CI: 0.418–0.698)." (PMID 35734412, 2022).
colon adenocarcinoma (1 paper, 2022). "Mutations of SKIDA1, CLK1, NSFL1C, OR2A5, EDEM3, and OR51V1 were associated with significant deregulation of DDX20 gene expression pattern in colon adenocarcinoma patients." (PMID 36011315, 2022).
tumor (3 papers, 2017 to 2025). "Further characterization of the mechanisms of SKIDA1’s tumor suppressive function in ccRCC and expanded characterization of other VHL-pRb regulated transcriptional targets in ccRCC is needed to appreciate the scope and mechanism of pRb dysregulation in ccRCC." (PMID 40240354, 2025). "To further validate SKIDA1 as a clinically relevant target in ccRCC, we performed immunoblot analysis of additional ccRCC tumor and patient-matched normal samples, genotyped to confirm VHL mutation in all tumor samples." (PMID 40240354, 2025). "Alternatively, SKIDA1 activators, though not yet identified, represent another promising avenue for inducing tumor cell death." (PMID 40240354, 2025).
SKIDA1 also shares sentences with these, for which no sentence is quoted: cancer (2 papers); glioma (1).